ACOX2 (acyl-CoA oxidase 2)
Diseases named in the same sentence as ACOX2 in open-access papers (continued):
Sharing a sentence is not in itself a finding about the gene and the disease.
squamous cell carcinoma (1 paper, 2022). A carcinoma arising from squamous epithelial cells. "When stratified according to histology, downregulation of ACOX2 was found to be significant in both Adenocarcinomas (LUAD) (p = 0.0151) and Squamous Cell Carcinomas (LUSC) (p = 0.0008) respectively." (PMID 35999530, 2022).
steatosis (1 paper, 2021). Increased lipid within the cytoplasm of cells. "ACOX2 plays an important role in the AOP of steatosis as it is responsible for the degradation of long-branched fatty acids and a downregulation of this gene might therefore be responsible for the accumulation of triglycerides in hepatocytes." (PMID 33575850, 2021).
Zellweger syndrome (1 paper, 2015). "The Acox2 gene encodes for the branched-chain acyl-CoA oxidase protein, and deficiency of this enzyme results in the accumulation of branched fatty acids and may lead to Zellweger syndrome, severe mental retardation, and death in children." (PMID 25844808, 2015).
tumor (14 papers, 2013 to 2025). "ACOX2 mRNA expression is linked to a number of mutated genes, and associations between ACOX2 expression and tumour mutational burden and immune cell infiltration were explored." (PMID 35999530, 2022). "Our study highlights the oncogenic property of Acox2 deficiency in tumor progression as those of our previous and other studies." (PMID 35351852, 2022). "In this manuscript we linked dysregulated expression of ACOX2 in NSCLC to altered infiltration of immune cells into the tumour environment." (PMID 35999530, 2022). "Using the methodology described by Feng and Shen, we analysed the correlation between ACOX2 expression and biomarkers of tumour burden mutation, genes associated with either the DNA Damage Response (DDR) pathway or the Mismatch Excision Repair (MMR) pathway as a proxy for TMB." (PMID 35999530, 2022). "Thus, Kcr changes caused by Acox2 deficiency might be directly involved in the metabolic switch that is essential for tumor transformation in liver tissues of Acox2−/− mice." (PMID 35351852, 2022). "There was an inverse relationship between NAC1 and ACOX2 expressions in the tumor specimens of ERONs." (PMID 40430078, 2025). "We assessed the expression ACOX2 mRNA in a panel of surgically resected fresh-frozen normal/tumour matched patient samples from Stage I and II patients by qPCR." (PMID 35999530, 2022). "Acyl-CoA oxidase 2 (ACOX2) has been proposed to inhibit tumor progression and the metastasis of HCC trough a PPARα-dependent pathway." (PMID 35954274, 2022). "We subsequently interrogated the CPTAC dataset for LUAD and the results show that ACOX2 protein levels are significantly reduced in tumour samples compared to normal." (PMID 35999530, 2022). "Through the GSEA analysis, we found that the PPARα pathway was activated in tumor samples with higher ACOX2 expression." (PMID 33414412, 2021). "ACOX2 overexpression, using a subcutaneous xenograft tumor model, indicated a tumor suppressor role in HCC." (PMID 33414412, 2021). "ACOX2, as a β-oxidation gene, participated in lipid degradation, and could be used as both tumor suppressor gene and tumor promoter gene." (PMID 38965225, 2024). "We found that the positive rate of ACOX2 was much lower in tumor tissues than control tissues." (PMID 33414412, 2021). "Consistently, ACOX2 overexpression decreased tumor growth and lung metastasis in xenograft tumor." (PMID 33414412, 2021). "The present study implicated that NAC1 may contribute to the development of ERONs as a transcriptional repressor by regulating ACOX2 expression via specific binding sites on the promoter, providing a novel insight into the NAC1/ACOX2 axis as a potential therapeutic target of this tumor type." (PMID 40430078, 2025). "In addition, to our knowledge, this study is the first report to prove the prognostic impact of the NAC1/ACOX2 axis; high levels of NAC1 combined with low levels of ACOX2 were associated with worse prognosis in patients with ERONs, signifying a novel prognostic marker for this tumor type." (PMID 40430078, 2025). "Compared to the normal tissue in the TCGA cohort, ACOX2 (P < 0.001), PTGS1 (P < 0.001), PTGS2 (P < 0.001), and PPARGC1A (P < 0.001) were downregulated, while HAO1 (P < 0.001) was upregulated in tumor samples." (PMID 38706909, 2024). "Notably, NAC1 has been found to suppress the expression of genes associated with tumor suppression and differentiation, thereby fostering tumor cell proliferation and survival, consistent with the present finding that NAC1 suppresses ACOX2 expression to contribute to the development of ERONs." (PMID 40430078, 2025).
cancer (11 papers, 2010 to 2025). A tumor composed of atypical neoplastic, often pleomorphic cells that invade other tissues. "An analysis of the effect of KRAS mutation on the expression of ACOX2 in TCGA datasets for commonly mutated cancers clearly demonstrates significant upregulation of ACOX2 mRNA in both LUAD and LUSC subtypes." (PMID 36980522, 2023). "Previous research has demonstrated that reduced ACOX2 activity can lead to a shift towards anabolic processes, providing cancer cells with the necessary building blocks for rapid proliferation and growth." (PMID 40430078, 2025). "While research on the involvement of ACOX2 in the onset of CM remains limited, relevant studies have been conducted in other types of cancer." (PMID 38279987, 2024). "Surprisingly ACOX2 was described as a gene commonly upregulated across several TCGA cancer datasets including NSCLC." (PMID 35999530, 2022). "The results clearly demonstrate that low expression of ACOX2 in cancer cells significantly inhibits the expression of PPARA, but not PPARD and PPARG." (PMID 33414412, 2021). "In this study, combined effects of FH (E404D) and ACOX2 (R409H) on metabolic switch from fatty acids to glucose were remarkably distinct, which might be an essential precondition to trigger the occurrence of PMCTs and mimic the Warburg effect, a hallmark of cancer metabolism." (PMID 30062063, 2018). "At present, there are few studies about the function of ACOX2 in cancers." (PMID 33414412, 2021). "One key family of enzymes in this process are the peroxisomal acyl-CoA oxidases (ACOX1, ACOX2 and ACOX3), the expression of which has been shown to be dysregulated in some cancers." (PMID 35999530, 2022). "When cancer cells experience metabolic stress, NAC1 is overexpressed, which may enhance its binding to the ACOX2 promoter to repress ACOX2 expression, leading to decreased fat catabolism and increased fat anabolism." (PMID 40430078, 2025). "The FPKM values of ACOX2 and PPKAA2 were lower in cancer tissues than in adjacent normal tissues (P < 0.05; P < 0.01), again indicating the potential involvement of these genes." (PMID 41184824, 2025).
ACOX2 also shares sentences with these, for which no sentence is quoted: cardiovascular disease (2 papers); Cognitive impairment (2); colon adenocarcinoma (2); peroxisomal disorder (2); adenocarcinoma (1); bladder cancer (1); cardiac malignant tumor (1); colorectal cancer (1); endometriosis (1); Hypertension (1); IgA nephropathy (1); infection (1); metabolic disease (1); Obesity (1); osteosarcoma (1); ovarian neoplasm (1); pancreatic adenocarcinoma (1); peroxisome biogenesis disorder (1); prostate adenocarcinoma (1); protein deficiency (1); pulmonary fibrosis (1); rectal adenocarcinoma (1); rheumatoid arthritis (1); type I diabetes (1); vitiligo (1).